ACHE (acetylcholinesterase (Yt blood group))
Diseases named in the same sentence as ACHE in open-access papers (continued):
Sharing a sentence is not in itself a finding about the gene and the disease.
tumor (45 papers, 2008 to 2025). "In many of these disorders, increased levels of AChE have been linked to increased metastatic potential of the tumor cells." (PMID 34500749, 2021). "The results indicated that tumours with AChE activity below 1.801 mU/mg were statistically associated with poorer OS (p = 0.014), but not with shorter DFS (p = 0.560)." (PMID 25956553, 2015). "We applied immunohistochemistry, immunoblotting, MTT-viability, invasion, flow-cytometric-cell-cycle-assays, phospho-kinase arrays, multiplex ELISA and xenografted mice to assess the impact of AChE inhibition on PCa cell growth and invasiveness, and tumor-associated inflammation." (PMID 33357230, 2020). "Moreover, tumours with low AChE activity and high BChE activity were associated with shorter patient overall survival." (PMID 25956553, 2015). "Interestingly, higher tumor grades, i.e. a poor tumor differentiation, were associated with significantly lower AChE IHC scores (G1: 1.5 ± 0.2, G2: 1.1 ± 0.3, G3: 1.0 ± 0.4), suggesting a spontaneous loss of AChE in increasingly aggressive PCa." (PMID 33357230, 2020). "In vivo, Tf-PL/AChE achieved a tumor inhibition rate of 77.47% in xenograft models, significantly reducing tumor volume (517.14 ± 112.63 mm3) and showing prolonged tumor retention." (PMID 40321406, 2025). "On the other hand, AChE was found to be involved in tumor suppression by its participation in apoptosis indicating its potential role as a marker and regulator of apoptosis and tumor development." (PMID 37147356, 2023). "Regarding expression level, ACHE was more highly expressed in tumor tissues and correlated with inferior clinical outcome in ccRCC." (PMID 36825082, 2023). "Consistent with the knockout effect of ACHE, the overexpression of ACHE undergoing apoptosis indicated the inhibition of tumor proliferation." (PMID 37842037, 2023). "In the case of liver hepatocellular carcinoma (LIHC), the ACHE gene was overexpressed in the tumor and significantly increased with the tumor stage." (PMID 37760598, 2023). "We compared the expression status of these markers in the tumor and normal sample groups from NSCLC, while the results indicated that ACHE (p = 2.4E−10) and the other six genes all had significantly high expression levels in tumor group." (PMID 37842037, 2023). "In brain tumors, it has been found that AChE activity increases considerably as tumor malignancy progresses." (PMID 37760598, 2023). "High AChE activity in tumors affects the tumoral microenvironment because of ACh hydrolysis, and inflammation increases, favoring tumor development." (PMID 37760598, 2023). "In lung adenocarcinoma (LUAD), the expression of ACHE is elevated in the primary tumor, and the increase is observed at all stages." (PMID 37760598, 2023). "This review aims to outline the extraction and purification methods, structural characteristics and biological activities (such as immunoregulatory, anti-tumor, prebiotic, anti-oxidant, anti-inflammatory and inhibition of AChE activity) of LPs." (PMID 35958258, 2022). "To determine the clinical relevance of the key regulators ChAT and AChE in ACh metabolism, we performed immunohistochemical analysis on 20 paired tumor biopsies taken before and after EGFR-TKI therapy." (PMID 36048538, 2022). "In this study, the tumor targeting ability and growth inhibitory effect of Tf-PL/AChE were evaluated through a series of in vitro and in vivo experiments." (PMID 33482834, 2021). "ACHE is responsible for the enzymatic degradation of acetylcholine (ACh), and a decrease in its activity is positively associated with HCC tumor size and stage." (PMID 34451900, 2021). "Turriane-type cyclophanes are efficient agents for the cleavage of supercoiled DNA; they inhibit acetylcholinesterase (AChE) and exhibit high cytotoxic activity against KB and L1210 tumor cell lines." (PMID 34445489, 2021).
tumor (continued). "At present, a variety of properties, such as antioxidant, anti-tumor, antibacterial, and anti-inflammatory, inhibit acetylcholinesterase (AChE), and other activities of chemical components have been found from Celtis by international scholars." (PMID 35480217, 2021). "In animals in which AChE was blocked prophylactically, only 15% of the specimens showed penetrating tumor growth, whereas 80% of the control group showed tumor infiltration into neighboring organs." (PMID 33357230, 2020). "In order to evaluate the invasive potential of PCC in vivo, we assessed the proportion of xenografted mice that showed penetrating tumor growth into neighboring organs, i.e. kidneys and lungs, following therapeutic or prophylactic treatment with AChE-blockers." (PMID 33357230, 2020). "Both extracts exhibited a similar degree of AChE-inhibitory properties, while limited cytotoxic activity was observed towards the considered human tumor cell lines." (PMID 32575531, 2020). "In a previous study published by our group, the crude extracts of T. lutea displayed promising antioxidant properties, inhibition of acetylcholinesterase (AChE), and cytotoxicity against tumor cell lines (HepG2)." (PMID 33227960, 2020). "Different authors have reported marjoram’s antibacterial and antiviral properties, antioxidant and anti-acetylcholinesterase (AChE) activities, and also anti-metastatic and anti-tumor growth effects." (PMID 32993114, 2020). "The concentration of exosomes released by tumor cells was determined measuring the activity of AChE with the Exocet kit and by Nanoparticle tracking analysis (NTA)." (PMID 31186484, 2019). "Since, after injection we kept the embryos at 33 °C for tumor development, we also checked AChE activity at this temperature and found a 12-fold higher activity in wild-type embryos." (PMID 29371671, 2018). "Future studies also should test the tumor size differences in transplantation of isogenic cell lines in which ACHE mRNA is knocked down or over-expressed within the same background." (PMID 29371671, 2018). "The contents of flavonoids especially anthocyanin in EPHF were increased significantly compared with the PHF, and EPHF exhibited strong antioxidant, AChE inhibitory activity and cytotoxicity on human tumour cells." (PMID 28284186, 2017). "So, whilst poorly differentiated tumours were able to maintain or even increase the levels of the three AChE mRNA types, all of them were found decreased in well or moderately differentiated tumours." (PMID 25956553, 2015). "The information relative to AChE and BChE involvement in cell proliferation and differentiation makes it possible that ChEs take part in tumour development." (PMID 25956553, 2015). "A possible pathological significance for the changing ChE activity was examined by comparing AChE and BChE activities in tumours and their clinico-pathological parameters." (PMID 25956553, 2015). "Afterwards, considering that the expression of AChE and BChE genes frequently changes with development and/or proliferation states, the possibility remained that tumours with distinct differentiation grading displayed unequal patterns of AChE or BChE mRNAs." (PMID 25956553, 2015). "Nevertheless, the possibility remains that the lower AChE activity in HNSCC represents a specific feature of the cell type from which the tumour emanates." (PMID 25956553, 2015). "PCR data indicated that while well and moderately differentiated tumours contained lower AChE mRNA, the opposite applied for poorly differentiated tumours." (PMID 25956553, 2015). "Oncolytic adenoviral vector ZD55 seems to be a stimulus for initiating the anti-tumor effect of AChE protein." (PMID 25220382, 2014). "Since AGS cells failed to form subcutaneous xenografts, we evaluated the anti-tumor effect of AChE in the MGC80-3 xenografts." (PMID 25220382, 2014). "The inhibitory activities against AChE and cytototicities towards tumor cell lines of compounds 1–10in vitro." (PMID 23877026, 2013).
tumor (continued). "The largest constitutive exon of number 2 of ACHE showed pronounced expression compared to the other ACHE exons in exon array data sets from cerebellum, breast, liver, muscle, kidney, heart, pancreas and both normal and tumor colons (gene structure under 6B)." (PMID 18545673, 2008). "ACHE is an acetylcholine hydrolase that plays a complex role in tumor biology." (PMID 40963562, 2025). "It has been demonstrated that (AChE) was significantly downregulated in the cancerous tissues of 69.2% of HCC patients, and low (AChE) expression in HCC was correlated with tumor aggressiveness, an elevated risk of postoperative recurrence, and a low survival rate." (PMID 38429330, 2024). "Analyses of molecular forms of AChE have been performed in some neoplasms and adjacent healthy tissues to determine whether there were differences in the profile of the molecular forms." (PMID 37760598, 2023). "The decrement in AChE activity could increase the local levels of ACh; this could contribute to tumor development." (PMID 37760598, 2023). "Based on these data, it could be assumed that the decrease in AChE activity and the increase in the local concentrations of ACh could contribute to tumor aggressivity." (PMID 37760598, 2023). "Although it is known that the AChE protein could be a potential tumor suppressor, it is imperative to elucidate the mechanism that decreases the synthesis and activity." (PMID 37760598, 2023). "This trend suggests a relationship between ACHE gene overexpression and tumor development." (PMID 37760598, 2023). "The purpose of this paper is to comprehensively summarize the extraction and purification methods, structural characteristics, and multiple biological activities (e.g., immunomodulatory, anti-tumor, prebiotic, anti-oxidant, anti-inflammatory, and AChE inhibitory activities) of LPs." (PMID 35958258, 2022). "However, recent studies have shown the non-classical function of the enzyme as a potential tumor suppressor and regulator of apoptosis, which support the involvement of AChE in the regulation of tumor development." (PMID 33917200, 2021). "Thus, in order to investigate the potential application of A. subhirsutum extracts in AD and cancer chemoprevention, the AChE inhibitory properties and cytotoxicity on tumor cells were also investigated." (PMID 32575531, 2020). "Hence, we concluded that advanced tumor stages were characterized by low cholinergic input due to low ChAT expression, and yet also by suppression of the degrading enzyme AChE." (PMID 33357230, 2020). "Herein, we observed an increase in AChE activity, which is in general associated to neurotoxicity; however, the literature also suggests that AChE may display antitumor activity, in addition to correlating tumor malignancy with low activity of AChE." (PMID 31878135, 2019). "Likewise, the regulators of cell differentiation and proliferation, VEGFA, DLG4, CDK, NRP2 and ACHE, were also found to be down-regulated in the mtDNA-depleted tumours but presented higher levels of expression in the cells." (PMID 30208958, 2018). "The median follow-up time was 29.04 months (range 6–60 months), and a cut-off value of the 50th percentile of AChE (1.801 mU/mg protein) and BChE (2.967 mU/mg protein) was set-up when comparing activity values in tumours with OS and DFS rates of the study population." (PMID 25956553, 2015). "ZD55-AChE repressed tumor growth in vivo, and the anti-tumor efficacy is greater than Ad.AChE." (PMID 25220382, 2014). "However, in a tumor with high AChE activity, these effects could decline due to the high amount of hydrolysis of ACh." (PMID 37760598, 2023).
tumor (continued). "Accordingly, tissue expression scores of AChE did not associate with different UICC tumor stages." (PMID 33357230, 2020). "Thus, tumor cell-released Hsp70 and Hsp90 were associated with CD9/TSG101/AchE-positive EVs." (PMID 28928431, 2017). "Both ACHE and VNN1 were found to be significantly upregulated in AEG tumor tissues compared with NAT, and ACHE expression was correlated with the grade of tumor differentiation." (PMID 40963562, 2025). "Sodium selenite treatment upregulated pro-apoptotic, apoptotic, and tumor suppressor genes such as ATF3, FOSB, GADD45B, DUSP8 and ACHE, and downregulated tumor cell survival genes such as SCD, LRP1, RAB31, SRPX2, PDK1 and CSGALNACT1." (PMID 36059619, 2022). "Based on our findings, indirect activation of cholinergic signaling via AChE inhibition is not sufficient to achieve a survival benefit in PCa, although it resulted in a prominent suppression of the tumor-associated inflammation in the tumor, and a drop of serum cytokine levels." (PMID 33357230, 2020). "We detected tumor-released EVs from conditioned medium and serum that are consistent to exosomes in terms of size (~110 nm) and marker proteins (CD9/TSG101/AchE)." (PMID 28928431, 2017). "However, the role of AChE in tumor progression remains unclear." (PMID 26932526, 2016). "Thus, using their oncolytic adenoviral vector ZD55-AChE to overexpress AChE, the authors found ZD55-AChE induced apoptosis in GC cells at low doses and inhibited GC stem cell growth and tumor progression in vivo." (PMID 38067366, 2023). "On the other hand, ACHE and CASP9 have a protective effect against tumor progression." (PMID 36838660, 2023). "In rectum adenocarcinoma (READ), the expression of ACHE decreases in the tumor, and the decrease is independent of the stage in which it is found." (PMID 37760598, 2023). "Notably, ACHE has an abnormal expression status in the NSCLC dataset, which suggests the significantly high level in tumor samples compared with normal samples." (PMID 37842037, 2023). "Lack of AChE expression has been reported in some tumor cells that are not sensitive to apoptosis induction suggesting that decreased AChE levels act to protect the cells against apoptosis." (PMID 36142659, 2022). "Another study has found that it is also a promising tumor suppressor, therefore, the inhibition of the AChE would not be beneficial for the suppression of carcinogenesis." (PMID 35241672, 2022). "While AChE does not appear to initiate apoptosis, several reports have shown that it acts as a tumor suppressor, in part, by the catalytic hydrolysis of Ach." (PMID 36142659, 2022). "This suggests that zebrafish expression ACHE rather than tumor production of ACHE influences tumor growth." (PMID 34451900, 2021). "Some tumor cells show no expression of AChE and are not sensitive to apoptosis induction suggesting that low levels of AChE protect the cells against apoptosis." (PMID 32193421, 2020). "Our findings suggested that ache mutants exhibited larger tumor volumes in comparison with healthy siblings regardless of the cell line used although they showed differential cholinesterase (ACHE/BCHE) expression." (PMID 29371671, 2018). "Loss of Rab27 abolished the release of EVs as well as Hsp70 and Hsp90 without altering Hsp70/90 and AChE expression by tumor cells, resulting in a blockade of the catabolic response in myotubes to tumor cell-conditioned media." (PMID 28928431, 2017). "However, in rectal and colon adenocarcinoma, AChE is repressed, and there is no relation between low expression and tumor progression or prognosis." (PMID 37760598, 2023). "Low AChE activity in tumors directly affects the tumor rather than the microenvironment." (PMID 37760598, 2023). "Notably, this effect was induced without surgical vagotomy, but only through non-neuronal, tumor cell intrinsic AChE inhibition." (PMID 33357230, 2020).
tumor (continued). "This simultaneous suppression of the ACh-synthesizing and ACh-degrading intrinsic mechanisms in PCa may explain the lack of a prognostic effect of tumor AChE levels in established mouse and human PCa." (PMID 33357230, 2020).
infection (25 papers, 2014 to 2026). The state of being infected such as from the introduction of a foreign agent such as serum, vaccine, antigenic substance or organism. "In this study, we used paraoxon, a highly specific AChE inhibitor, to regulate the immune response to an infection caused by Salmonella enterica serovar Typhimurium (S. typhimurium)." (PMID 29616040, 2018). "Therefore, the presence of an intense inflammatory infiltrate observed in natural infection in both acute and chronic besnoitiosis may be associated with an increase in AChE activity." (PMID 34551803, 2021). "AChE, a neural enzyme, was also measured in the head in Experiment B. Immune function was altered in response to both infection and irradiation, as evidenced by a decrease POX activity and increase ALP activity (Experiment B)." (PMID 41511945, 2026). "Immune enzymes (PO, CAT, POD) were initially activated but later inhibited, while detoxification enzymes (GSTs, CarE, AChE) were largely suppressed, weakening the insect’s defense against infection." (PMID 40870660, 2025). "CarE and AChE activities remained largely unchanged or were significantly suppressed across infection timelines following both O1 and N8 treatments, while GST activity was notably upregulated at 72–96 h in both treatment groups." (PMID 40870660, 2025). "There was an increase in AChE activity during infection, leading to a pro-inflammatory response and an increase in M1 and M2 mACh receptors in the BNZ group, showing that the treatment interacted with the cholinergic pathway." (PMID 39459036, 2024). "By the 5th days of post-infection, the extracts of A. nilotica, E. guineensis 1, and 2 increases the activity of AChE of the Nosema infected honeybee by about 28.12, 42.19, and 54.6%, respectively." (PMID 39550385, 2024). "Possible functions of AChE in vertebrate neuro-immune systems include restoring immune system homeostasis following an infection or other inflammatory reaction." (PMID 37670115, 2023). "On certain days after infection, the activity of AChE in lymphocytes and whole blood, the level of cytokines, the level of immunoglobulins and the protein profile by electrophoresis were assessed." (PMID 35216144, 2022). "As a result of the infection, a decrease in AChE activity was observed, while the level of ACh was increased." (PMID 35216144, 2022). "Given a previous in vitro study showing that polyclonal anti-AChE antibodies cause complement-dependent killing of schistosomula, the reduction in male worm burden observed in the rSjAChE vaccinated/challenged mice may be a consequence of immature males being killed at an early stage of infection." (PMID 30115897, 2018). "Nevertheless, in our current system, the net effect of over-expressing nematode AChE during systemic infection of mice with our vehicle is polarisation to a Th1 environment and skewing of macrophages to an M1 phenotype." (PMID 27802350, 2016). "Accordingly, recent studies have demonstrated that the use of AChE inhibitors suppress systemic inflammation and enhance the survival of animals exposed to lipopolysaccharides or infection." (PMID 24763113, 2014). "The replication-deficient adenoviral vector Ad.AChE was less effective than the oncolytic vector ZD55-AChE, requiring a higher multiplicity of infection for a similar effect, suggesting that the OV form may be more practical." (PMID 38067366, 2023). "Detoxification enzymes (CarE, AChE, GST, and CYP450) displayed a pattern of early activation followed by decline, indicating an initial host defense response that weakened as infection progressed and fungal toxins accumulated." (PMID 41009055, 2025). "We found that the activities of CarEs, AchE, and GST initially increased but then decreased, and the maximum activities of CarEs, AchE, and GST were observed on the 2nd day or 3rd day after infection." (PMID 31576242, 2019).